CRP (C-reactive protein)
Diseases named in the same sentence as CRP in open-access papers (continued):
Sharing a sentence is not in itself a finding about the gene and the disease.
type 2 diabetes (continued). "In addition, this study reconfirm the previously found associations between high CRP levels and the increased risk for type 2 diabetes." (PMID 28258520, 2017). "Higher CRP levels increase susceptibility to metabolic diseases such as type 2 diabetes." (PMID 28750055, 2017). "CRP gene variants have been independently associated with serum lipid levels and individuals carrying the risk allele for CRP also encounter higher lipid levels and risk of type 2 diabetes." (PMID 27177774, 2016). "In another study, individuals at high risk of type 2 diabetes, using Hemoglobin A1c (HbA1c) criterion, showed an unfavorable inflammatory profile of five inflammatory markers (high-sensitivity hs-CRP, ESR, fibrinogen, white blood cell WBC count, and complement C3) as compared with control subjects." (PMID 27581604, 2016). "Many studies have shown association between CRP and type 2 diabetes." (PMID 27581604, 2016). "Whether CRP also mediates the association between smoking quantity and type 2 diabetes is still unresolved and is the subject of this study." (PMID 25105149, 2014). "This study examined whether CRP mediates the association between smoking quantity and type 2 diabetes." (PMID 25105149, 2014). "A longitudinal study design is needed to assess whether cigarette smoking is a factor that directly induces CRP and indirectly causes type 2 diabetes." (PMID 25105149, 2014). "We therefore could not exclude the possible influence of antidiabetic medications on the association of CRP with cigarette smoking and type 2 diabetes." (PMID 25105149, 2014). "It is widely recognised that CRP is an independent risk factor for type 2 diabetes." (PMID 25105149, 2014). "This study provides further evidence that smoking quantity is positively associated with type 2 diabetes and suggests that the association between smoking and type 2 diabetes might be mediated by CRP." (PMID 25105149, 2014). "Moreover, Krzyzanowska and colleagues showed that ADMA is a new indicator of cardiovascular risk in type 2 diabetics and that it, independently of other known risk factors, increases the predictive value of CRP for cardiovascular disease." (PMID 24804267, 2014). "Higher CRP and IL-6 concentrations were also associated with higher incidence of type 2 diabetes." (PMID 23843750, 2013). "For example, if type 2 diabetes were to cause an elevation of CRP levels, then it is conceivable that some type 2 diabetes SNPs might show association in a GWAS meta-analysis of CRP." (PMID 24204319, 2013). "We confirmed the strong and positive association between lipocalin-2 and CRP levels observed in previous studies, suggesting elevated serum lipocalin-2 in prediabetes and type 2 diabetes might associate with chronic inflammation." (PMID 22292925, 2012). "CRP is an inflammatory marker that has been associated with increased incidence of type 2 diabetes in several studies, prompting the inclusion of hs-CRP in a type 2 diabetes risk prediction score." (PMID 23251619, 2012). "A high GI diet, therefore, could not explain the positive association between CRP and risk of type 2 diabetes by increasing CRP concentrations." (PMID 21804937, 2011). "Specifically, we found that high concentrations of procalcitonin were associated with fewer days alive and free of delirium and coma (meaning fewer days alive and free of brain dysfunction), and CRP showed a trend toward a similar relationship, after adjusting for potential confounders." (PMID 21366899, 2011). "The analysis confirmed that CRP at baseline was associated with an increased risk of type 2 diabetes after adjustment for age, sex, BMI, waist, systolic blood pressure, diastolic blood pressure, and HDL (RRCRP Q4 versus Q1: 1.76 (95%CI 1.27, 2.45); Ptrend < .01)." (PMID 21804937, 2011). "We investigated, therefore, whether GI or GL is associated with CRP and subsequently with risk of type 2 diabetes in an elderly Dutch population." (PMID 21804937, 2011).
type 2 diabetes (continued). "In addition this study also demonstrates an association between resistin and CRP, a marker of inflammation in type 2 diabetic patients." (PMID 15998471, 2005). "However, we did find associations between genetic liability to MDD and increased C-reactive protein levels, lipid levels, and type II diabetes, offering evidence that MDD might lead to long-term dysregulated immunometabolic pathways." (PMID 37693619, 2024). "The severity and prognosis of exacerbated inflammatory responses in conditions like cardiovascular disease (CVD), type 2 diabetes mellitus (T2DM), hemorrhagic stroke, and sepsis within the context of COVID-19 pneumonia have been notably associated with CRP." (PMID 38304653, 2024). "In addition, further research is needed to explore how various factors may mediate the association between type 2 diabetes and mental health disorders, such as blood concentrations of C-reactive protein (CRP)." (PMID 38617916, 2024). "Interestingly, patients with type 2 diabetes show underlying low-grade inflammation, which may be reflected by elevated serum-CRP levels." (PMID 37107100, 2023). "Furthermore, we investigated whether ABL and hs-CRP could associate with type 2 diabetes with the aim of using it as a new screening method." (PMID 35805792, 2022). "On the other hand, CRP is a clinical marker of low grade inflammation and this may underlie an increased CV risk known as residual inflammatory index, recently described for patients with type 2 diabetes." (PMID 32867226, 2020). "Thus, inflammation as indicated by high CRP and low adiponectin may alter the risk for the development of type 2 diabetes after pregnancy complicated by GDM." (PMID 29951553, 2018). "Also, high CRP level is reported to be a risk factor for progression type 2 diabetes." (PMID 26153197, 2015). "CRP is regarded as a reliable down-stream marker of inflammation, and although IL-6 is suggested to be one of its main inducers, we could not find any association of CRP with CV events and death in this population with type 2 diabetes." (PMID 23987834, 2013). "Several studies have confirmed the role of subclinical inflammation in the course of atherosclerosis and have associated CRP levels with the metabolic syndrome (MS), type 2 diabetes mellitus (T2DM) and increased risk for cardiovascular disease." (PMID 23367494, 2013). "Therefore, allelic scores indexing CRP which are based on this GWAS meta-analysis will also show association with type 2 diabetes even though the direction of causation may be from the disease to the biological intermediate." (PMID 24204319, 2013). "It has been proposed that the C-reactive protein (CRP) has clinical utility as a biomarker in predicting risk of cardiovascular events and a predictive value in the progression of type 2 diabetes (T2D)." (PMID 23049543, 2012). "In patients with type 2 diabetes mellitus, aerobic exercise during 16 weeks was associated with a decrease in bodyweight by only 1.3 kilograms and by lower plasma concentrations of IL-6, IL-18, CRP and resistin showing an anti-inflammatory effect of exercise with only marginal weight reduction." (PMID 21276223, 2011). "Overall, the SII-NLR-PLR axis remained the most stable inflammatory core in type 2 diabetes, whereas CRP and Ferritin exhibited variable, drug class-dependent associations." (PMID 41598626, 2026). "This systematic review evaluates the prognostic role of high-sensitivity CRP (hs-CRP) in predicting cardiovascular outcomes among individuals with type 2 diabetes." (PMID 41835631, 2026). "The case of a 61-year-old patient with type 2 diabetes exemplified this, presenting with prolonged inflammation, persistent elevation of C-reactive protein (CRP), and delayed normalization of hematological parameters." (PMID 41303165, 2025).
type 2 diabetes (continued). "In a recent prospective cohort study of patients with type 2 diabetes, individuals with high periodontal inflammatory burden demonstrated significantly elevated serum IL-6 and CRP levels, which correlated with increased coronary artery calcification scores." (PMID 41007869, 2025). "Chronic sterile inflammation serves as a connection between type II diabetes mellitus and CAD, as evidenced by significantly elevated levels of high-sensitive C-reactive protein (HS-CRP) in the CAD group compared to the control and high-risk groups." (PMID 40830908, 2025). "With these caveats in mind, interesting epidemiological studies have observed elevated circulating levels of IL-1β and IL-1-dependent CRP, IL-6 and IL-1Ra in individuals with type 2 diabetes." (PMID 39496966, 2025). "These immunomodulatory properties have been supported by clinical studies in populations with chronic inflammatory conditions such as type 2 diabetes and polycystic ovary syndrome, with reductions in markers like C-reactive protein (CRP)." (PMID 40932867, 2025). "High fibrosis score was the most substantial risk factor for all-cause mortality in participants with MASLD, whereas high CRP concentration was the most substantial risk factor for all-cause mortality in participants with NAFLD, followed by type 2 diabetes." (PMID 41171731, 2025). "Our results corroborate these findings, as both the ART and ART + type II diabetes groups exhibited consistently elevated levels of inflammatory biomarkers, including CRP, IL-6, TNF-α, and fibrinogen, compared to the control group." (PMID 39860995, 2025). "A cohort of people with type 2 diabetes treated with empagliflozin for 24 weeks had decreased serum levels of hs-CRP and increased levels of anti-inflammatory IL-10." (PMID 40004134, 2025). "Applying the HVP model to data from the UKB, we found that horizontal pleiotropy significantly contributes to the genetic correlations between MetS and traits such as type 2 diabetes, C-reactive protein, sleep apnoea, and cholelithiasis." (PMID 40956352, 2025). "In the CANOSSA trial, canagliflozin lowered hs-CRP after 3, 6, and 12 months of therapy in subjects with type 2 diabetes and chronic heart failure." (PMID 40004134, 2025). "Long-term intake of yoghurt proteins has also been linked to reductions in CRP, blood glucose, total cholesterol, LDL cholesterol, and triglycerides among patients with type 2 diabetes and nephropathy." (PMID 41011276, 2025). "Elevated levels of pro-inflammatory cytokines, especially IL-6, along with CRP and other markers, are common targets for intervention in managing type 2 diabetes." (PMID 41011276, 2025). "In particular, IL-6 levels are independently correlated with C-reactive protein (CRP) in adults with type II diabetes, indicating a link between inflammation and metabolic dysfunction." (PMID 41011276, 2025). "Several meta-analyses reported that GLP-1RAs reduced inflammatory biomarkers, such as C-reactive protein (CRP) and TNFα, and oxidative stress biomarkers, such as malondialdehyde, in subjects with type 2 diabetes." (PMID 39861190, 2025). "Individuals with type 2 diabetes exhibited higher levels of the inflammation marker C-reactive protein (p<0.001) and the heart failure marker NT-proBNP (p<0.001) in the morning than in the afternoon." (PMID 40580209, 2025). "Advanced fibrosis was the most serious risk factor for all-cause mortality in MASLD, and high C-reactive protein concentration was the most serious risk factor for all-cause mortality in NAFLD, followed by type 2 diabetes." (PMID 41171731, 2025). "Regarding cardiovascular risk factors in FH, 63 (51%) selected lipoprotein (A), 87 (71%) smoking, 27 (22%) C-reactive protein, and 84 (68%) type 2 diabetes." (PMID 40786346, 2025). "These mediators, which include C-reactive protein, interleukin-6 (IL-6), and TNF-α, raise the risk of developing chronic diseases like type 2 diabetes and cardiovascular disease." (PMID 40509530, 2025).
type 2 diabetes (continued). "Beyond CRP/Alb, hematologic indices such as NLR, PLR, and SII have been linked to renal injury and cardiovascular outcomes in type 2 diabetes." (PMID 41302334, 2025). "as a function of age and according to type 2 diabetes and low-grade inflammation status (CRP < or ≥ 2 mg/L)." (PMID 38730445, 2024). "The goal of the research is to ascertain howTumour Necrosis Factor (TNFα), Type 2 diabetes has several etiopathogenic factors, including Interleukin-6 (IL-6), Interleukin-10(IL-10), and C - reactive protein (CRP)." (PMID 39132231, 2024). "Previous diet intervention studies in patients with type 2 diabetes revealed reduced BMI, blood pressure, fasting glucose, total and low density cholesterol, CRP and IGF-1 levels in a cohort of 100 participants, particularly in those at risk for disease." (PMID 38600065, 2024). "Sedentary behavior and the associated accumulation in visceral adiposity lead to increases in cytokines and inflammatory markers such as IL-6 and CRP, especially in patients with type 2 diabetes." (PMID 38725572, 2024). "Another nested case-control study of 550 middle-aged women followedfor four years found that those in the top quartile of the C-reactive protein distribution had a nearly 16-fold higher chance ofacquiring type 2 diabetes than those in the bottom quartile." (PMID 40092874, 2024). "As previously reported, this SNP affects CRP protein levels, which influence type 2 diabetes and CVD15." (PMID 38184750, 2024). "Several other studies have investigated the relationship between inflammatory markers such as CRP and IL-6, and glycaemic traits and type 2 diabetes using MR, however, the results are inconsistent." (PMID 38730445, 2024). "Our findings in T1D adults also differ from previously reported decreased CRP levels after several years of healthy eating patterns in patients with type 2 diabetes." (PMID 38999806, 2024). "In animal models, quercetin (a flavonoid) and lycopene (a carotenoid) significantly decreased standard assay CRP in insulin-resistant and type 2 diabetic rats, respectively." (PMID 38999806, 2024). "In randomized controlled trials, adhering to a Mediterranean, healthy, and/or anti-inflammatory diet decreased circulating CRP (hs- and standard assay) in adults with type 2 diabetes compared to a usual or habitual diet." (PMID 38999806, 2024). "After scaling in patients with type 2 diabetes, high-sensitivity C-reactive protein (hs-CRP), IL-1ß, IL-6 concentrations and HbA1c decreased." (PMID 38573898, 2024). "The results of an investigation demonstrated astrong correlation between type 2 diabetics and TNFα, IL-6, CRP, and IL-10, receiving care at SMHS Hospital who is of Kashmiriorigin." (PMID 39132231, 2024). "High-sensitivity C-reactive protein (hs-CRP) is a marker of systemic inflammation and a predictor of type 2 diabetes and CVDs." (PMID 39021797, 2024). "Another strong statistically significant correlation was identified between high CRP levels at discharge, strongly associated (p < 0.001) with elevated LDH and fibrinogen levels in patients with type 2 diabetes and SARS-CoV-2 viral infection." (PMID 38929867, 2024). "The cumulative incidence of CVD death at age 80 years was comparable in individuals with a CRP ≥ 2 mg/L or with type 2 diabetes (3.7% or 4.0%, respectively)." (PMID 38730445, 2024). "Systemic levels of TNF-a, IL-1b, IL-6, and CRP are elevated in both type 1 and type 2 diabetes patients, which is a result of the chronic activation of pro-inflammatory pathways within insulin-target cells." (PMID 38904046, 2024). "In subjects with type 2 diabetes, a diet high in AGEs increased inflammatory markers, i.e., C-Reactive protein, TNF-α, VCAM-1 and oxidative stress." (PMID 39518960, 2024). "Previous studies have described the temporal changes in biomarkers such as BMI, fasting glucose, LDL, HDL, triacylglycerol and C-reactive protein (CRP) preceding a type 2 diabetes diagnosis." (PMID 39078488, 2024).
type 2 diabetes (continued). "Among all participants, sex, BMI, waist circumference, glucose, HbA1c, ASAT, CRP, systolic blood pressure, type 2 diabetes and red meat intake were directly, and physical activity inversely associated with EAT thickness (Model 1)." (PMID 38796541, 2024). "In another study on type 2 diabetes patients, curcumin improved the serum lipid profile, CRP, and adiponectin levels." (PMID 37547100, 2023). "Clinical data also show that systemic levels of pro-inflammatory cytokines, including tumor necrosis factor (TNF)-a, interleukin (IL)-1b, IL-6, and CRP are elevated in patients with both type 1 and type 2 diabetes." (PMID 36769405, 2023). "In type II diabetes mellitus, dapagliflozin lowered CRP, IL-6 levels, and ferritin, though for CRP contradictory results exist." (PMID 37278822, 2023). "Long sleep duration was found to be associated with elevated inflammation marker C-reactive protein (CRP) in the Nurses’ Health Study, which enrolled 935 women with type 2 diabetes." (PMID 37489354, 2023). "A total of 19 samples (healthy: 1; type 1 diabetes: 4; type 2 diabetes: 12) were excluded from the dataset due to CRP levels above 10 mg/L indicating acute inflammatory processes." (PMID 37189645, 2023). "Compared with patients with COPD alone, patients combined with OSA were overweight, had lower CRP, better airway obstruction, and less AE during the 12 months before enrolling into the study, and were more likely to have type 2 diabetes." (PMID 37008211, 2023). "Increased CRP levels reflect probably both subclinical inflammation present in patients with type 2 diabetes and decreased 25(OH)D levels." (PMID 37623831, 2023). "In parallel with our findings, the meta-analysis reported that exercise significantly decreased inflammatory cytokine CRP and IL-6 in patients with type 2 diabetes after a brief period of exercise (12–14 weeks)." (PMID 38004306, 2023). "CRP is an indicator of acute and chronic phase inflammation and increases chronic diseases such as type 2 diabetes, cardiovascular disease, and sarcopenia." (PMID 35361818, 2022). "Subjects with low vitamin D levels (<20 mmg/dl) were more likely to be female, have type 2 diabetes, higher HbA1c, D-dimer and ferritin levels and lower oxygen saturation, albumin and C-reactive protein." (PMID 35155539, 2022). "As far CRP is concerned, we co-authored a multicenter European study demonstrating that the CRP serum levels were significantly lower in HNF1A-MODY than in type 1 or type 2 diabetes." (PMID 36104811, 2022). "For example, vitamin E has been shown to reduce serum CRP and monocyte IL-6 levels in type 2 diabetic patients, and vitamin E has been shown to play a more important role than vitamin C in improving oxidant/antioxidant imbalance in HD patients." (PMID 35740095, 2022). "Another clinical trial study on type 2 diabetic patients has shown that oral consumption of ginger (1600 mg/d) for 12 weeks ameliorated insulin sensitivity and reduced C-reactive protein (CRP) and prostaglandin E2 (PGE2)." (PMID 35949312, 2022). "This association remained significant in a multivariable model after adjustment for all parameters which significantly correlated with GIP levels (BMI, CRP and type 2 diabetes) (p = 0.0311)." (PMID 35123462, 2022). "Reductions in CRP were also similar in participants with type 2 diabetes (STEP 2) and participants with normoglycaemia and prediabetes (STEP 1 and 3)." (PMID 36467859, 2022). "Specifically, previous publications have described that weight loss due to calorie restriction reduces oxidative stress and adipose tissue inflammasome activation in mice and humans with type-2 diabetes, which is reflected in reductions of CRP and TNFα levels." (PMID 35158762, 2022). "Background: to evaluate the association between type 2 diabetes and periodontal disease severity using the rate of alveolar bone loss (ABL) and high-sensitivity C-reactive protein (hs-CRP) value as indices." (PMID 35805792, 2022).